NPC2 (NPC intracellular cholesterol transporter 2)
Description:
Intracellular cholesterol transporter which acts in concert with NPC1 and plays an important role in the egress of cholesterol from the lysosomal compartment. Unesterified cholesterol that has been released from LDLs in the lumen of the late endosomes/lysosomes is transferred by NPC2 to the cholesterol-binding pocket in the N-terminal domain of NPC1. May bind and mobilize cholesterol that is associated with membranes. NPC2 binds cholesterol with a 1:1 stoichiometry. Can bind a variety of sterols, including lathosterol, desmosterol and the plant sterols stigmasterol and beta-sitosterol. The secreted form of NCP2 regulates biliary cholesterol secretion via stimulation of ABCG5/ABCG8-mediated cholesterol transport (By similarity).
Synonyms: He1; NP-C2; EDDM1
Tractability: Small molecule: a structure with a bound ligand is known. Antibody: UniProt places it where antibodies can reach, with high confidence; its Gene Ontology location is reachable by antibodies, with high confidence; UniProt predicts a signal peptide or a membrane-spanning region. PROTAC: ubiquitination databases record sites on it; its protein half-life has been measured.
Gene: Protein-coding gene on chromosome 14 (74,476,192 to 74,494,177, reverse strand). Ensembl gene ENSG00000119655.
Subcellular location: Secreted; Endoplasmic reticulum; Lysosome
Pathways (Reactome):
Immune System: Neutrophil degranulation
Transport of small molecules: LDL clearance
Gene Ontology:
Molecular function: cholesterol binding; cholesterol transfer activity; enzyme binding; lipid transporter activity; protein binding; sterol binding
Biological process: cholesterol efflux; cholesterol homeostasis; cholesterol transport; intracellular cholesterol transport; intracellular sterol transport; lysosome to ER cholesterol transport; response to virus; glycolipid transport; phospholipid transport; regulation of isoprenoid metabolic process; sterol transport
Cellular component: endoplasmic reticulum; extracellular exosome; extracellular region; late endosome; lysosomal lumen; lysosome; azurophil granule lumen
Genetic constraint (gnomAD): Loss-of-function variants: 17 observed, 17.91 expected, observed/expected ratio (o/e) 0.95, 90% interval 0.65 to 1.42. The upper end of that interval is the gene's LOEUF score, 1.42, which puts it in group 5 of 6, group 1 being the genes least tolerant of losing a copy. Missense variants: 167 observed, 184.31 expected, observed/expected ratio (o/e) 0.91, 90% interval 0.8 to 1.03. Synonymous variants: 75 observed, 68.82 expected, observed/expected ratio (o/e) 1.09, 90% interval 0.9 to 1.32.
Gene-disease validity (ClinGen):
ClinGen rates the evidence that NPC2 causes each of these diseases.
Niemann-Pick disease, type C2 (autosomal recessive): Definitive.
Homologues: Orthologues: chimpanzee NPC2 (100% identical), macaque NPC2 (100% identical), mouse Npc2 (80% identical), dog NPC2 (79% identical), rat Npc2 (79% identical), rabbit NPC2 (76% identical), pig NPC2 (74% identical), guinea pig NPC2 (74% identical), zebrafish npc2.1 (58% identical), zebrafish npc2.2 (57% identical), tropical clawed frog npc2 (56% identical), Drosophila melanogaster Npc2a (34% identical).
Diseases named in the same sentence as NPC2 in open-access papers:
NPC2 is named in the same sentence as 156 diseases in open-access papers, as found by Europe PMC text mining. Sharing a sentence is not in itself a finding about the gene and the disease. The quoted sentences say what the papers report.
Niemann-Pick disease type C (87 papers, 2012 to 2026). NPC is a complex lipid storage disease mainly characterized by the accumulation of unesterified cholesterol in the late endosomal/lysosomal compartment. "Niemann-Pick Disease type C is a fatal autosomal recessive lipid storage disorder caused by NPC1 or NPC2 gene mutations and characterized by progressive, disabling neurological deterioration and hepatosplenomegaly." (PMID 38291356, 2024). "Mutations in either NPC1 (95% of cases) or NPC2 (5% of cases) genes cause Niemann-Pick disease type C (NPC), resulting from deficiencies of sphingomyelin phosphodiesterase 1 gene expression." (PMID 39416542, 2024). "NPC2 mutations cause a cholesterol and sphingolipid storage disorder known as Niemann-Pick disease type C (NPC), which has severe implications for cognitive, liver, and spleen function." (PMID 38964324, 2024). "A similar, but much rarer disorder, Niemann-Pick disease, type C2 (NPC2, MIM 607625), is caused by impaired function of NPC2." (PMID 38673803, 2024). "Niemann–Pick disease type C (NPC) is a distinct subtype of the disease caused by mutations in the NPC1 or NPC2 gene." (PMID 39525762, 2024). "Mutations in NPC1 and NPC2 genes are the cause of Niemann-Pick disease, type C that leads to lysosomal accumulation of cholesterol." (PMID 39106189, 2024). "Niemann-Pick disease is an autosomal recessive lysosomal lipid storage disorder disease caused by mutations in either Niemann-Pick disease type C1 (NPC1) or the NPC2 gene." (PMID 39416542, 2024). "NPC2 encodes the Niemann-Pick disease type C2 protein and homozygous LOF mutations of this gene cause Niemann-Pick disease." (PMID 37020259, 2023). "Niemann–Pick Disease Type C (NP-C) is an autosomal recessive atypical lysosomal lipid storage disorder caused by mutations of either of two genes: NPC1 (95% of cases) or NPC2." (PMID 37629187, 2023). "The mutation of NPC1 and NPC2 genes induces Niemann-Pick disease type C (NPDC), which is a hereditary disease and causes progressive neurodegeneration, developmental disability, hypotonia, and ataxia." (PMID 38136141, 2023). "Pathologically, mutations of the NPC1 and NPC2 genes induce the fetal inherited disorder Niemann-Pick disease type C (NPDC), wherein cholesterol aberrantly accumulates in lysosomes." (PMID 38136141, 2023). "The accumulation of cholesterol in lysosomes is reminiscent of the phenotypes in human lysosomal storage diseases, such as Niemann-Pick disease type C (NPC) caused by pathogenic variants in NPC1 or NPC2, which block cholesterol export from the lysosome." (PMID 37736739, 2023). "Patients with Niemann-Pick type C disease carry mutations either in NPC intracellular cholesterol transporter 1 or 2 (NPC1or NPC2) gene, which together are responsible for lysosomal cholesterol efflux." (PMID 36409725, 2022). "Niemann-Pick disease type C (NPC) is a rare lysosomal neurovisceral storage disease caused by mutations in the NPC 1 (95%) or NPC2 (5%) genes." (PMID 35086560, 2022). "Niemann–Pick disease type C (NPC) is a recessive hereditary disease caused by mutation of the NPC1 or NPC2 gene." (PMID 33466390, 2021). "Mutations in human NPC2 leads to the development of Niemann–Pick disease type C, an autosomal recessive disorder." (PMID 34050187, 2021). "Niemann–Pick disease type C (NPC) is an autosomal recessive disorder that develops as a result of NPC1 or NPC2 gene mutation (95% and 5% of patients, respectively) and has been identified as a severe disease associated with lysosomal dysfunction." (PMID 33466390, 2021). "Niemann−Pick disease type C (NPC) is a rare neurodegenerative disorder caused by autosomal recessive loss-of-function in either the NPC1 (95% of cases) or NPC2 (5% of cases) genes." (PMID 34377675, 2021). "Niemann-Pick type C2 disease is caused by mutations in the NPC2 gene, which is mapped on the q-arm of chromosome 14 at position 24.3 in humans." (PMID 33924575, 2021).
Niemann-Pick disease type C (continued). "Niemann−Pick disease type C (NPC) is a rare neurodegenerative disorder caused by a recessive mutation in the NPC1 or NPC2 gene, in which patients exhibit lysosomal accumulation of unesterified cholesterol and glycolipids." (PMID 34377675, 2021). "Niemann-Pick disease type C (NPC) is an autosomal recessive disorder caused by mutations of NPC1 or NPC2, which encode the proteins that are responsible for intracellular cholesterol trafficking." (PMID 32898135, 2020). "Niemann-Pick disease, type C (NPC) is a neurodegenerative lysosomal storage disorder caused by mutations in the NPC1 or NPC2." (PMID 33311479, 2020). "Mutations of either NPC intracellular cholesterol transporter 1 or 2 (Npc1 or Npc2) cause the Niemann-Pick Type C disease (NPC), which is a rare recessive neurological disorder." (PMID 30866987, 2019). "Niemann Pick Type-C disease (NPC) is an inherited lysosomal storage disease (LSD) caused by pathogenic variants in the Npc1 or Npc2 genes that lead to the accumulation of cholesterol and lipids in lysosomes." (PMID 31605022, 2019). "Loss of function mutations in the NPC2 gene lead to a lysosomal disorder known as Niemann–Pick disease type C, which causes an increased accumulation of lipids in cellular compartments and leads to cell death." (PMID 31167461, 2019). "The NPC2 genes (Niemann–Pick disease type C2) encode the proteins that are potentially involved in intracellular and extracellular transport of sterols." (PMID 31117933, 2019). "Niemann-Pick type C disease (NPC) is a genetically determined neurodegenerative metabolic disease resulting from the mutations in the NPC1 or NPC2 genes." (PMID 31197681, 2019). "Niemann-Pick disease type C (NP-C) is a neurodegenerative lysosomal lipid storage disease caused by autosomal recessive mutations in the NPC1 or NPC2 genes." (PMID 30285904, 2018). "Niemann Pick disease type C (NP-C) is a neurovisceral lysosomal storage disorder caused by autosomal recessive mutations in the NPC1 (≥95% of cases) or the NPC2 gene and is characterized by impaired trafficking of cholesterol and sphingolipids." (PMID 30285904, 2018). "In the larval exposure, we also detected increased expression of hdmh, erg1, cp51a, and npc2 (encoding the proteins squalene epoxidase, and cytochrome P450 51A, Niemann-Pick disease, type C2, respectively) at the latest stages examined (14 and 18 dph)." (PMID 28117666, 2017). "Selected examples are cases with ethylmalonic encephalopathy (ETHE1), Niemann–Pick disease type C2 (NPC2), and pyruvate dehydrogenase E1-alpha deficiency (PDHA1)." (PMID 27848944, 2017). "Their inherited deficiencies lead to Niemann-Pick disease type C. NPC2 can pick up cholesterol directly from inner membranes and transfer it to NPC1 or other vesicular membranes." (PMID 25339683, 2014). "Niemann pick type C disease is a rare neurovisceral lysosomal storage disorder caused by mutations in either NPC1 or NPC2 genes." (PMID 25396745, 2014). "Niemann Pick disease type C (NP-C) is a rare autosomal recessive disorder that results from mutations in either the NPC1 or the NPC2 gene." (PMID 25145893, 2014). "Niemann-Pick disease type C (NP-C) is caused by mutations in either the NPC1 or the NPC2 gene, it is a rare neurovisceral lysosomal storage disorder (LSD) which leads to progressive neuropsychiatric deterioration and in the majority of cases, premature death." (PMID 25479233, 2014). "Niemann–Pick Type C2 (NPC2, downregulated in the lake ecotype) is an apparent homolog of a human gene that, when mutated, results in Niemann–Pick type C2 disease, a condition that results from accumulation of low-density lipoprotein cholesterol in lysosomes." (PMID 22423327, 2012). "A polymorphism in the NPC1 or NPC2 gene is associated with lysosomal cholesterol accumulation and, consequently, with the Niemann–Pick disease type C, a human neurodegenerative lysosomal lipid storage disorder associated with the early onset of Crohn’s Disease." (PMID 40943172, 2025).
Niemann-Pick disease type C (continued). "Niemann–Pick disease type C (NPC) is another LSD associated with significant CNS involvement caused by mutations in the NPC1 or NPC2 gene, leading to impaired intracellular trafficking and the accumulation of cholesterol and glycosphingolipids within lysosomes." (PMID 39525762, 2024). "Niemann–Pick disease type C (NPC) is a fatal neurodegenerative condition caused by genetic mutations of the NPC1 or NPC2 genes that encode the NPC1 and NPC2 proteins, respectively, which are believed to be responsible for cholesterol efflux from late-endosomes/lysosomes." (PMID 38254990, 2024). "In humans, mutations in either NPC1 or NPC2 lead to the development of Niemann–Pick disease type C (NPC disease), a lysosomal storage disorder with a broad spectrum of visceral and neurological symptoms resulting from cellular accumulation of cholesterol and glycolipids." (PMID 34050187, 2021). "Moreover, Niemann-Pick disease type C is a neurodegenerative disorder with mutation in the NPC1 or NPC2 (Niemann-Pick disease, type C1 or C2) genes, which encode proteins involved in cholesterol transport." (PMID 31357643, 2019). "NPC2 regulates the transport of cholesterol through the late endosomal/lysosomal system and mutations in this gene have been associated with Niemann-Pick disease type C2, a disease with a broad range of visceral, neurological and psychiatric clinical presentations." (PMID 28904337, 2017). "Increasing endolysosomal cholesterol levels in Niemann-Pick disease type C, caused by an inherited defect of a steroid transfer protein, either NPC2 or NPC1, are accompanied by an accumulation of SM, glycosphingolipids, sphingosine, and the anionic endolysosomal marker phospholipid, BMP." (PMID 25339683, 2014). "Niemann–Pick disease type C (NP-C) is a rare inherited lysosomal storage disorder caused by autosomal recessive mutations in either the NPC1 gene (in 95% of cases) or the NPC2 gene, and is characterized by progressive neurological deterioration and premature death." (PMID 23773996, 2013). "Niemann-Pick disease, type C is an autosomal recessive, fatal, neurodegenerative disorder caused by pathological variants in NPC1 or NPC2." (PMID 41726996, 2026). "Niemann-Pick disease, type C (NPC), is an inherited fatal lysosomal storage disorder caused by a mutation in the NPC1 or NPC2 genes and characterized by impaired lysosomal cholesterol export." (PMID 41811855, 2026). "Niemann–Pick disease type C1 and C2 are caused by mutations in the NPC1 and NPC2 gene loci, leading to impaired intracellular cholesterol trafficking and subsequent accumulation of cholesterol and sphingolipids in lysosomes." (PMID 41511290, 2025). "Niemann–Pick type C disease (NPC) is a neurodegenerative disorder classified into types C1 and C2 depending on the respective human gene (NPC1 or NPC2) that is mutated." (PMID 41511290, 2025). "Niemann–Pick disease type C (NPC) is a rare and fatal neurological disorder caused by mutations in Npc1 or Npc2, with Npc1 accounting for 95% of cases." (PMID 39202426, 2024). "Niemann-Pick Disease type C is divided into type C1 and type C2, which are caused by pathogenic mutations of the NPC1 gene and NPC2 gene, respectively." (PMID 38291356, 2024). "Niemann-Pick disease type C (NPC) is an autosomal recessive, progressive disorder resulting from variants in NPC1 or NPC2 that leads to the accumulation of cholesterol and other lipids in late endosomes and lysosomes." (PMID 39061081, 2024). "Niemann-Pick disease type C1 (NP-C1) is a rare and devastating recessive inherited lysosomal lipid and cholesterol storage disorder caused by mutations in the NPC1 or NPC2 gene." (PMID 39263569, 2024). "Acid sphingomyelinase deficiencies encompass types A and B, and Niemann–Pick disease type C includes types C and D. This illness results from deficiencies in either NPC1 or NPC2 transport proteins, leading to lipid storage diseases." (PMID 37629187, 2023).
Niemann-Pick disease type C (continued). "Niemann‐Pick disease, type C is a lipid storage disorder caused by the deficiency of one of two proteins, NPC1 (NPC1 gene) or NPC2 (NPC2 gene), although NPC1 mutations are prevalent in the patient population." (PMID 37014126, 2023). "Recently, CE1 has been identified as the second gene of Niemann-Pick type C disease (NPC2) involved in cholesterol efflux from lysosomes." (PMID 35327169, 2022). "Niemann-Pick disease type C (NPC) is a rare, autosomal recessive, lysosomal storage disease, resulting from mutations in the cholesterol trafficking proteins NPC1 or NPC2, which is characterized by progressive neurodegeneration and hepatic dysfunction." (PMID 36636588, 2022). "The lysosomal storage disorders Niemann-Pick disease Type C1 (NPC1) and Type C2 (NPC2) are rare diseases caused by mutations in the NPC1 or NPC2 gene." (PMID 33445799, 2021). "Niemann-Pick disease, type C (NPC) is a childhood-onset, lethal, neurodegenerative disorder caused by autosomal recessive mutations in the genes NPC1 or NPC2 and characterized by impaired cholesterol homeostasis, a lipid essential for cellular function." (PMID 34592985, 2021). "Niemann–Pick disease type C (NPC) is an autosomal recessive, neurodegenerative disease caused by mutations in either the NPC1 or NPC2 genes." (PMID 34535129, 2021). "In Niemann-Pick disease, type C (NPC), excess cholesterol accumulation in the endo-lysosomal compartment is caused by defects in one of two lysosomal proteins, either NPC1 or NPC2." (PMID 31999726, 2020). "Niemann–Pick disease type C (NPC) is the rare neurodegenerative disease caused by mutations of NPC1 (~95%) and NPC2 (~5%) that lead to the progressive neurodegeneration of the central nervous system." (PMID 33311479, 2020). "Niemann-Pick disease, type C2 (NPC2) had the largest expression in PTC (86.97 median gene expression units), up-regulated by 7.24x with respect to NOR." (PMID 32887258, 2020). "Niemann-Pick disease type C (NP-C) is a rare, progressive neurodegenerative disease caused by mutations in the NPC1 or the NPC2 gene, which lead to impaired cholesterol metabolism." (PMID 29871644, 2018). "This test identified a homozygous mutation of the NPC2 gene (OMIM 601015), which has been reported to be pathogenic and responsible for Niemann-Pick disease type C2 (NPD-C2)." (PMID 29928259, 2018). "Niemann-Pick disease type C (NP-C) is a rare, progressive neurodegenerative disease caused by mutations in the NPC1 or the NPC2 gene." (PMID 29871644, 2018). "Niemann–Pick disease type C (NPC) is a fatal autosomal recessive neurovisceral disorder due to mutation in NPC1 and NPC2 genes leading to alterations in trafficking of endocytosed cholesterol." (PMID 28095804, 2017). "Niemann-Pick disease type C (NP-C) is a rare, autosomal recessive neurodegenerative disease caused by mutations in either the NPC1 or NPC2 genes." (PMID 28222799, 2017). "Cholesterol has been found located into non-polar protein cavities, for example for the lysosomal protein NPC2, responsible for Niemann-Pick type C disease." (PMID 29168745, 2017). "Niemann-Pick disease type C (NPC) is caused by defects in cholesterol efflux from lysosomes due to mutations of genes coding for NPC1 and NPC2 proteins." (PMID 24775609, 2014). "Niemann Pick disease type C (NP-C; OMIM#257220 and OMIM#607625) is a rare autosomal recessive, multisystemic, neurodegenerative condition caused by mutations in the NPC1 or the NPC2 gene." (PMID 25145893, 2014). "Niemann–Pick disease type C (NP-C) is a rare, autosomal-recessive, progressive neurological disease caused by mutations in either the NPC1 gene (in 95% of cases) or the NPC2 gene." (PMID 23773996, 2013). "Niemann-Pick Type C disease (NPC) is a lethal, autosomal recessive disorder caused by mutations in the NPC1 and NPC2 cholesterol transport proteins." (PMID 23144769, 2012).